IL6 (interleukin 6)
Diseases named in the same sentence as IL6 in open-access papers (continued):
Sharing a sentence is not in itself a finding about the gene and the disease.
periodontitis (continued). "Since calprotectin induces the secretion of sIL-6R in macrophages, calprotectin-mediated HGF-macrophage crosstalk may enhance the IL-6 responsiveness of HGFs, leading to the progression of periodontitis." (PMID 36359741, 2022). "The synergistic responses of HGFs by IL-1β and IL-6/sIL-6R may promote periodontal inflammation by inducing the expression of gp130, resulting in the progression of periodontitis." (PMID 36359741, 2022). "Additionally, it was discovered that knocking down lncZFY-AS1 reduced inflammatory factors TNF-α, IL-1β, and IL-6 in the periodontitis model." (PMID 35659193, 2022). "In tissue sections, immunohistochemical staining was conducted to reveal inflammatory cytokines (IL-1β and IL-6) in the periodontal tissues of mice, which showed significant reductions of positive rates under Rd treatments, compared with the periodontitis group (p < 0.05)." (PMID 35480231, 2022). "Immunohistochemical staining of rat periodontal tissue sections with IL-1β and IL-6 antibody showed that, compared to the control group, there were obvious positive areas in the periodontitis group, with proportions of IL-1β-positive cells up to 9.06% ± 5.42% and IL-6 up to 20.29% ± 4.97%." (PMID 36430410, 2022). "Interestingly, orthodontic tooth movement further increased the periodontitis-induced upregulation of IL-6 in our study." (PMID 34024010, 2022). "In addition, METTL3 knockdown in LPS-stimulated periodontitis cells reduces IL-6 and IL-8 production." (PMID 36555481, 2022). "Another possible link might be related to interleukin-6 (IL-6), which was described to be important in the pathogenesis of both periodontitis and the cytokine storm." (PMID 36676965, 2022). "Periodontitis is a bacterial infectious disease, and its pathological cascade is regulated by many inflammatory cytokines secreted by immune or tissue cells, such as interleukin-6." (PMID 36359741, 2022). "Therefore, in this study, we investigated the effect of Pg-OMVs on the production of IL-6 and IL-8 in gingival epithelial cells and compared this with Pg-LPS, which is a key factor in periodontitis development." (PMID 36289904, 2022). "IL-1β and IL-6 concentrations were statistically higher in periodontitis patients and may be used as potential tools in periodontitis diagnosis." (PMID 35368315, 2022). "In addition, the greater part of these cytokines are present in periodontitis, mainly IL-1, IL-6, and TNF-α, which can lead to tissue destruction and the consequent loss of insertion." (PMID 35225864, 2022). "Furthermore, in the present study, the levels of miR-1246 in saliva of patients with chronic periodontitis were positively correlated with the levels of IL-1β, IL-6, IL-17, and TNF-α, indicating a correlation between the two." (PMID 35942384, 2022). "However, the mRNA and protein levels of F4/80, MCP1, and IL-6 were downregulated by periodontitis in DIO mice relative to that of the HF control group." (PMID 36060644, 2022). "Therefore, the proinflammatory cytokines TNF-α, IL-1β, and IL-6 play a key role in the occurrence and development of periodontitis." (PMID 36546940, 2022). "Studies revealed that by causing peripheral CD4+ T helper cells to give rise to excessive amounts of pro-inflammatory cytokines, including IL-1β and IL-6, P. gingivalis could help in better understanding severe periodontitis." (PMID 36289921, 2022). "During the active phase of periodontitis, locally produced inflammatory cytokines such as interleukin-6 and tumour necrosis factor-α act systemically, which may lead to the progression of CKD." (PMID 35336824, 2022). "Moreover, according to a meta-analysis, chronic periodontitis patients have increased IL-6 levels in their gingival crevicular fluid, whereas there is no change in the levels following the hygienic phase of the periodontal treatment." (PMID 35628348, 2022).
periodontitis (continued). "The proportion of Il-1β (35.11% ± 4.53%, p < 0.0001) and IL-6 (41.02% ± 10.51%, p < 0.0001) positive areas and positive cells in untreated diabetic rats with periodontitis were significantly higher than those in untreated diabetic rats with periodontitis." (PMID 36430410, 2022). "Moreover, IL-4 and IL-6 are important cytokines in systemic inflammation, and studies have demonstrated that high levels of these cytokines are present in patients with periodontitis." (PMID 35225864, 2022). "Multiple mediators may have systemic effects on bone formation and bone resorption, the proinflammatory cytokine TNF- α、 IL-1 and IL-6 have been shown to be increased in patients with periodontitis." (PMID 36584175, 2022). "Untreated periodontitis results in increased levels of circulating bacteria and bacterial antigens, together with increased circulating levels of pro-inflammatory cytokines, such as interleukin-6 (IL-6), tumour necrosis factor-α (TNF-α) and oxygen radicals." (PMID 36612820, 2022). "These two cytokines may induce a number of inflammatory mediators such as IL-6, IL-8, MMP and prostaglandin E2 (PGE2), which is the most prominent prostaglandin implicated in the pathogenesis of periodontitis." (PMID 35903322, 2022). "Not surprisingly, the variants of IL1B and IL6 genes have been associated with other chronic inflammatory conditions such as periodontitis, cancer, osteoporosis, type 2 diabetes and diabetic nephropathy." (PMID 35964023, 2022). "Increased levels of TNF-α and IL-6 were also reported in human mothers with periodontitis." (PMID 35269617, 2022). "In this study, we have been unable to determine how TNF-α and IL-6 are regulated by PPARα in periodontitis, i.e., whether via the PPAR response element (PPRE) or via other PPARα target genes." (PMID 35293424, 2022). "Thus, the aim of the present study was to evaluate salivary concentrations of IL-1β, IL-6, MMP-8, and IL-10 in healthy and periodontitis patients and to assess the association between these biomarkers levels and clinical parameters in a Moroccan population." (PMID 35368315, 2022). "IL-6 also plays a key role in the initial and acute stages of periodontitis." (PMID 36430410, 2022). "Collectively, these findings suggest that reduced levels of CRP, IL-6, TNFα, and IL-1β after treatment of periodontitis could restore eNOS activity and NO bioavailability, resulting in improved endothelial dysfunction." (PMID 35874771, 2022). "Several previous studies indicated that higher prevalence of periodontitis in diabetic patients, and IL-6 might mediate periodontitis in diabetes." (PMID 35804048, 2022). "We speculated that IL-6 from periodontitis may play a role in the development/progression of cancer." (PMID 35804048, 2022). "An additional paper using PCR-based methods reported lack of statistically significant associations between IL6 SNPs and the amount of red complex species P. gingivalis, T. forsythia, and T. denticola in 326 patients with periodontitis in Italy." (PMID 35122548, 2022). "Alternatively, during periodontitis, inflammatory mediators and/or microbial components diffuse systemically from the oral cavity to the liver, enhancing cytokine production (e.g., IL-6) and acute phase protein responses (e.g., CRP), which then impact the fetal–placental unit." (PMID 35207626, 2022). "A large number of macrophages can be seen in the periodontal tissue of patients with periodontitis, and a large number of proinflammatory factors and bone resorptive factors, such as interleukin 1β, interleukin 6 (IL-6), and TNF-α, can be detected in gingival crevicular fluid." (PMID 35586136, 2022). "Previously, MMP-8 and IL-6 were identified as salivary biomarkers that increased in periodontitis." (PMID 35268009, 2022). "Moreover, in T2DM patients with chronic periodontitis, melatonin supplementation decreased the levels of IL-6 in serum." (PMID 35455066, 2022).
periodontitis (continued). "Indeed, it has been suggested that salivary IL-6 concentration increased significantly in periodontitis patients as compared to healthy controls and these levels increased with the progression of the disease." (PMID 35368315, 2022). "Endothelial dysfunction and injury caused by pro-inflammatory mediators of chronic periodontitis such as tumor necrosis factor-α (TNF-α), interleukin (IL)-1, and IL-6 could also affect the vasculogenic pathway resulting in erectile dysfunction." (PMID 35757444, 2022). "Moreover, METTL3 knockdown in LPS-stimulated periodontitis cells showed a reduced level of expression of the inflammatory cytokines, i.e., IL-6 and IL-8." (PMID 36555481, 2022). "More specifically, periodontitis, the most prevalent oral disease, can be detected early by monitoring the level of soluble urokinase-type plasminogen activator receptor (suPAR), or Interleukin-6 (IL-6), or bacterial specific antibodies in saliva." (PMID 33401680, 2021). "In the case of genomic regions with known genetic factors in PD, a systematic review and meta-analysis with more than 70,000 participants describes genetic variants in genes such as IL-1A, IL-1B, IL-6, IL-10, MMP-3, and MMP-9 were significantly associated with the risk of developing periodontitis." (PMID 34776994, 2021). "IL-6 may have a protective function in the inflammatory responses of periodontitis, and IL-17 has a weak relationship the inflammatory responses." (PMID 35046930, 2021). "However, overexpression of PTEN in experimental periodontitis mice attenuated the expression of IL-1, IL-6, and TNF-α." (PMID 34445604, 2021). "Nevertheless, during periodontitis, cytokines, such as Il-1β, IL-6 and TNF-α, are secreted in response to bacterial insult and could sustain the neuroinflammation process after passage through the blood–brain barrier." (PMID 34501984, 2021). "IL-6 may have protective function in the inflammatory responses of periodontitis, and IL-17 has a weak relationship with the inflammatory responses." (PMID 35046930, 2021). "Meanwhile, the expression of IL-6 in the liver of the periodontitis group was also enhanced." (PMID 35118014, 2021). "Previous studies confirmed that the expression levels of TNF-α and IL-6 were positively correlated with the severity of periodontitis, which was significantly increased at the site of periodontal inflammation, and its level was significantly reduced after treatment." (PMID 34819109, 2021). "In addition, periodontitis reduced IL-6, MCP-1, granulocyte-macrophage colony-stimulating factor, and interferon-γ (IFN-γ) expression in the brains of WT mice and reduced IL-10 expression in 5xFAD mice." (PMID 34445604, 2021). "In a murine periodontitis model induced by ligation, a HuR inhibitor could prevent bone resorption by reducing the level of IL-6." (PMID 34445604, 2021). "It should be considered that periodontitis, independently of any other pathology, raises IL-6." (PMID 33975613, 2021). "The concentrations of IL-6 in the saliva of periodontitis patients were significantly higher than that of healthy subjects, and the level of IL-6 in saliva was related to the clinical parameters of periodontitis patients." (PMID 34777632, 2021). "Previous findings reported increased IL-6 expression in chronic periodontitis." (PMID 34835489, 2021). "In the oral cavity, higher expression of HMGB1 was detected in gingival tissues and gingival crevicular fluid (GCF) of patients with periodontitis and peri-implantitis, which was accompanied by the elevated concentrations of pro-inflammatory cytokines, such as IL-1β, IL-6, and IL-8." (PMID 34573077, 2021). "Although there are controversial effectiveness signals with TNF inhibitors in improving chronic periodontitis, all papers about anti-IL-6 therapy clearly demonstrated articular, systemic, and also periodontal benefits with TCZ without any periodontal specific treatment." (PMID 33672771, 2021).
periodontitis (continued). "Systemic levels of inflammation mediators, such as CRP, TNF-α, and IL-6, are elevated in periodontal disease and may represent the link between diabetes and periodontitis." (PMID 34833990, 2021). "In addition, butyrate can dose-dependently induce the production of proinflammatory cytokines in gingival fibroblasts, including IL-6 and IL-11, which rescue T-cell from apoptosis and contributed to the development of periodontitis." (PMID 34869062, 2021). "The MAPK pathway is the upstream signaling intermediate to many inflammatory cytokines such as TNF-α, IL-1β, IL-6, and prostaglandin E2, and the blockage of this pathway could be beneficial for treating inflammatory diseases like chronic periodontitis and AD." (PMID 33869630, 2021). "LPS stimulation mainly augmented the expression levels of proinflammatory cytokines, including interleukin IL-1 beta (IL1β), tumor necrosis factor-alpha (TNFα), and IL-6, resulting in an inflammatory response and destruction of periodontal tissue during periodontitis." (PMID 34899921, 2021). "The unbalanced IL-6 levels could predict the early appearance of periodontitis more precisely than other periodontal pathogens in biofilms, and that serum IL-6 levels could be helpful in evaluating the degree extent of periodontitis." (PMID 34790237, 2021). "In addition, inflammatory cytokines such as IL-1, IL-6, and IL-8 play an important role in chronic periodontitis etiology, and increased concentrations of cytokines in sera from EBV-infected patients have been reported." (PMID 32178406, 2020). "Serum IL-6 levels were elevated, while those of IL-4/18 decreased in patients with periodontitis." (PMID 32698486, 2020). "Asiatic acid may also provide therapeutic latent energy for periodontitis through influencing the NF-κB signaling pathway and reducing the levels of related inflammatory factors (IL-8 ↓, IL-6 ↓, p-p65 ↓, p-IκBα ↓)." (PMID 33013406, 2020). "A recent study has revealed that IL-35 produced by regulatory T cells might block the development of periodontitis by reducing IL-17A-induced IL-6 and IL-8 expression." (PMID 33327639, 2020). "Our in vivo experiment found that RA can increase the expression of autophagy proteins TFEB and LC3A/B in the periodontitis lesion area, upregulate the secretion of inflammatory factors Tnfα and Il6, promote the infiltration of macrophages and finally aggravate bone destruction." (PMID 31737959, 2020). "Similarly, IL-6 levels have also been consistently shown to increase in relation to the extent of periodontitis." (PMID 32486269, 2020). "However, the inflammatory mediators the most involved in periodontitis, IL-1β, IL-6, and TNFα were measured, even partially measured, only in 4 studies." (PMID 32698391, 2020). "Importantly, in addition to the histopathological findings, we observed in the current study that ligature-induced periodontitis showed the increased concentrations of the cytokines IL-17, IL-6, and IL-4 in the heart of mice with gingival inflammation." (PMID 32327711, 2020). "It follows that low expression of M1 and M2 in PD patients would be the consequence of local and systemic pro-inflammatory loop lead by IL-6, IL1b and TNFα that down-regulate the macrophage polarization response, reflecting a perturbation in tissue repair in periodontitis." (PMID 32560235, 2020). "Follow-up data of 2.714 participants spanning five years from the cohort of Study of Health in Pomerania (SHIP), a population-based prospective cohort study in the northeast region of Germany, were analyzed for anthropometric measures, periodontitis, tooth loss, CRP and IL-6." (PMID 32486269, 2020). "In addition, the polymorphisms in NLRP3, IL1R, TNF, IL6, IL2, IL4 and IL4RA genes were associated with periodontitis in the males." (PMID 31978095, 2020).
periodontitis (continued). "In response to host injury and bacterial infection, IL-6 is produced and has a prominent role as an immunological mediator; however, it is known that there is excess production of this cytokine in patients with periodontitis compared with healthy individuals." (PMID 32244806, 2020). "Therefore, because high levels of IL-6 are greatly found in periodontitis patients, it becomes primordial to investigate the serum levels impact of periodontitis of such relevant pro-inflammatory cytokine in immunosuppressed patients." (PMID 32230707, 2020). "Furthermore, TNF-α, together with IL-6, plays a crucial role in establishing the inflammatory state in periodontitis; therefore, they can be considered specific markers of the disease." (PMID 33096800, 2020). "The hypothesis is that adipocytokine molecules are involved in the pathogenesis of inflammatory diseases; if true, individuals who are obese with periodontitis would present increased levels of visfatin, IL-6, and TNF-α in their GCF." (PMID 31365708, 2019). "IL-6 could alter osteocyte signaling toward osteoblasts and elicit periodontitis through facilitating osteoclastogenesis and bone resorption." (PMID 31608279, 2019). "Despite the absence of exacerbated ABL or osteoclastogenesis by overweight, the condition reduced periodontal macrophage number and partially suppressed pro- (i.e., TNF-α and IL-6) and anti-inflammatory cytokines (IL-10) in periodontium and circulation in periodontitis mice." (PMID 30719451, 2019). "Thus, we detected only five biomarkers with peak values in the periodontitis group: IL‐1ra, IL‐6, IL‐17, IFN‐γ, and VEGF." (PMID 31049215, 2019). "The involvement of IL-6 in periodontitis is well recognized." (PMID 31685798, 2019). "Also, studies found increased salivary levels of IL-6 in patients diagnosed with periodontitis and proved the fact that it influences osteoclast differentiation and bone resorption, being directly involved in tissue destruction." (PMID 30906485, 2019). "Concordantly with these studies performed in vitro, in periodontitis tissue samples, an increase in mRNA of IL-1β, IL-6, IL8, and TNF-α, regulated upon activation normal T cell expressed and secreted (RANTES) and monocyte chemotactic protein-1 (MCP-1), was observed, compared to healthy gingiva." (PMID 31049022, 2019). "IL-36γ could perpetuate gingival inflammation by increasing pivotal inflammatory cytokines in periodontitis (IL-1β, IL-6 and TNF-α) and alveolar bone resorption through an increase of the RANKL/OPG ratio in OECs." (PMID 31848404, 2019). "IL-6 induced by IL-17F or IL-17A may play a potential feedback loop in the pathogenesis of chronic periodontitis." (PMID 29670909, 2018). "Gene expression profiling in circulating monocytes in this experimental model showed that periodontitis induced a M1-like specific signature with high levels of TNF-α and IL-6 as compared to controls, indicating that a M1-like phenotype of macrophages is induced by periodontitis." (PMID 29507865, 2018). "Periodontitis-induced Il17a expression in the oral mucosa was completely inhibited in Il6–/– mice." (PMID 29453398, 2018). "Moreover, our results demonstrated that GCF and serum IL-6/IL-10 levels were higher in the CP group compared to healthy controls, which reflect local and systemic inflammation in periodontitis." (PMID 29489938, 2018). "IL-8 level was positively correlated with IL-6 level in patients with periodontitis." (PMID 29932110, 2018). "Additionally, the serum IL-6 and CRP levels have a positive association with the extent of periodontitis." (PMID 29980169, 2018). "Women with periodontitis exhibited significantly higher levels (p = 0.001) of salivary IL-6 and TNF-α compared with the healthy group: 25.1 (±11.2) pg/mL vs. 16.3 (±5.0) pg/mL and 29.7 (±17.2) pg/mL vs. 16.2 (±7.6) pg/mL, approximately 1.5 and 1.8 times more, respectively." (PMID 29740515, 2018).